CGAS (cyclic GMP-AMP synthase)
Diseases named in the same sentence as CGAS in open-access papers (continued):
Sharing a sentence is not in itself a finding about the gene and the disease.
gastric cancer (continued). "Abundant expression of BPLF1 in AGS-BX1 cells suggested efficient suppression of the cGAS-STING pathway in gastric carcinoma by EBV." (PMID 36802409, 2023). "Eventually, WEE1 inhibition triggers gastric cancer cell-intrinsic innate immunity through the activation of the cGAS/STING pathway, and thus, potentiates the anticancer effect of ICB therapy in MUS81 deficient gastric cancer cells." (PMID 34625086, 2021). "By employing cGAS high-expression gastric cancer cell lines, including AGS and MKN45, ectopic silencing of cGAS caused a significant reduction in the proliferation of the cells, tumor growth, and mass in xenograft mice." (PMID 37305397, 2021). "K-M survival analysis of the GEO database showed that GC patients with high cGAS expression had a worse prognosis, and nuclear accumulation of MRN complexes is associated with gastric cancer progression and poor prognosis, which is consistent with our results." (PMID 37305397, 2021). "Consequently, this study seeks to explore the effects of activating the cGAS‐STING signaling pathway in cisplatin‐resistant gastric cancer cells (SGC‐7901/DDP) using the STING agonist c‐di‐AMP in combination with the herbal medicine RG3." (PMID 39834553, 2025). "Collectively, these findings suggest that TRIM6 might contribute to the immunological regulation of gastric cancer by degrading the cGAS protein." (PMID 40817248, 2025). "Moreover, endogenous co-IP confirmed the interaction between TRIM6 and cGAS in gastric cancer cell lines." (PMID 40817248, 2025). "For example, high expression of RECQL4 in HCC or TRIM6 in microsatellite-stable gastric cancer potently suppresses the cGAS-STING pathway, leading to poor T-cell infiltration and likely blunting the response to ablation-driven vaccination without additional targeted modulation." (PMID 41295487, 2025). "Similarly, in both gastric cancer cells and mouse-transplanted tumor models, Anlotinib has shown efficacy in reducing tumor proliferation and metastasis by activating the cGAS-STING signaling pathway." (PMID 39063990, 2024). "Furthermore, it assesses the prospects of targeting the cGAS-STING pathway as a novel biotherapeutic strategy for gastric cancer." (PMID 39063990, 2024). "Furthermore, the upregulation of cGAS significantly exacerbated the prognosis of gastric cancer patients while improving radiotherapeutic outcomes." (PMID 37305397, 2021). "Furthermore, MUS81 inhibition increases replication stress and impairs replication stress-associated DNA repair, thereby accumulating cytosolic DNA in gastric cancer cells and activating cGAS/STING signaling." (PMID 34625086, 2021). "Using human AGS and MKN45 gastric cancer cell lines with siRNA knocked-down cGAS, it was demonstrated that cGAS-deficient gastric cells have reduced cell viability compared to non-gastric cancer cells with cGAS knocked down." (PMID 39050748, 2024). "This study aims to develop a cGAS-STING pathway-related genes (CSRs) prediction model to predict prognosis in gastric cancer (GC)." (PMID 33843442, 2021). "However, the function of cGAS in gastric cancer remains elusive." (PMID 37305397, 2021). "In the current study, we demonstrated that MK1775 increased the accumulation of cytosolic dsDNA and activation of TBK1 phosphorylation in MUS81-deficient gastric cancer cells, indicating that MK1775 could activate the innate immune response via the cGAS/STING pathway." (PMID 34625086, 2021). "Through genetic ablation studies in both MSS/MSI-low gastric cancer cell lines and murine MSS models, we show that TRIM6 deletion restores cGAS protein stability, reactivates the cGAS-STING-IFNβ signaling axis, and enhances antitumor immunity." (PMID 40817248, 2025).
gastric cancer (continued). "Metformin functions as a cGAS-STING agonist to promote immunotherapy through activating the cGAS-STING signaling pathway by blocking SOX2 and AKT phosphorylation in gastric cancer." (PMID 40552295, 2025). "In gastric cancer, EBV infection promotes the upregulation and secretion of OLFM4 by potentiating the cGAS-STING pathway, eventually augmenting the cancer progression." (PMID 40002690, 2025). "Increasing studies have revealed that cGAS-STING signaling contributes to the maintenance of gastric homeostasis and exerts protective effects in gastric cancer." (PMID 40621423, 2025). "In the gastric cancer cell lines MKN28 and SNU668, both of which are MSS or MSI-low, we knocked down TRIM6 and found that the cGAS protein level was elevated in shTRIM6 cells, whereas their mRNA expression remained unaffected." (PMID 40817248, 2025). "The authors concluded that cGAS overexpression leads to the activation of the MRN complex, thereby promoting genomic instability in gastric cancer cells and leading to tumor progression." (PMID 39050748, 2024). "Clinically, reduced expression of cGAS and STING in tumor cells correlates with poor survival in gastric cancer patients." (PMID 36394642, 2023). "Thereafter, the cGAS/STING pathway was evaluated, and the therapeutic value of MUS81 for immunotherapy of gastric cancer was determined." (PMID 34625086, 2021). "Therefore, we concluded that cGAS is involved in gastric cancer progression by fueling genome instability, implying that intervening in the cGAS pathway could be a practicable therapeutic approach for gastric cancer." (PMID 37305397, 2021). "Additionally, metformin activates the cGAS‐STING signaling pathway by inhibiting SOX2/AKT, offering potential for enhancing gastric cancer immunotherapy." (PMID 39834553, 2025). "Furthermore, it delves into future research prospects pertaining to the transduction of the cGAS-STING pathway and its pivotal role in facilitating the clinical translation of novel therapies for gastric cancer." (PMID 39063990, 2024). "Increased expression of cGAS has been found in gastric cancer tissue in comparison to normal gastric mucosa utilizing the TCGA database." (PMID 39050748, 2024). "For EBV+ gastric carcinoma, EBV might also participate in tumorigenesis by altering the cGAS-STING pathway." (PMID 36802409, 2023). "Additionally, we chose three gastric cancer cell lines: AGS, MKN45, and NCI-N87, interestingly cGAS showed higher mRNA levels than normal GES-1 cells, while NCI-N87 had nearly the same protein expression as GES-1." (PMID 37305397, 2021). "Although the WEE1 inhibitor MK1775 partly enhanced the anticancer effect of PD-L1 inhibitors by activating the cGAS/STING pathway, MUS81 targeting further amplified the anticancer effect of this combination strategy because of the elevated cytosolic dsDNA in gastric cancer cells." (PMID 34625086, 2021). "Additionally, SUMO-2/3 has been shown to stabilize NSUN2 and facilitate its nuclear transport in gastric cancer 48, while glucose-induced oligomerization and activation of NSUN2 promote TREX2 expression, suppressing cGAS/STING activation to regulate oncogenic activity in cancer cells." (PMID 41356184, 2026). "The gastric carcinoma SNU16 cell line expressed cGAS but not STING." (PMID 41509453, 2026). "Conversely, TRIM6 depletion in mouse (MTC) and human (MKN28) gastric cancer cells resulted in a significant increase in the mRNA levels of IFNB1 and its downstream genes CXCL10 and ISG15 (or Ccl5) under HT-DNA treatment, and these effects were abolished by simultaneous cGAS knockout." (PMID 40817248, 2025). "In gastric cancer cell lines, for instance, metformin has demonstrated the ability to not only inhibit the mTOR1 signaling pathway via classical AMPK-dependent or independent mechanisms but also to exhibit anti-tumor effects by activating the cGAS-STING pathway." (PMID 39063990, 2024).
gastric cancer (continued). "The expression of TP53BP1 positively correlated with the expression of cGAS, STING, and IRF3, while the expression of FANCD2 positively correlated with the expression of IRF3 and STAT6, suggesting the major role of DDR in SASP activation in early gastric cancers." (PMID 36061145, 2022).
Alzheimer disease (26 papers, 2021 to 2026). A progressive, neurodegenerative disease characterized by loss of function and death of nerve cells in several areas of the brain leading to loss of cognitive function such as memory and language. "Recently, pathogenic tau was shown to activate cGAS-STING and consequently upregulate IFN-I responses in microglia in a murine model of Alzheimer’s disease." (PMID 38785545, 2024). "The human Tau isoforms 410 and 441 exhibit intrinsic potential to stimulate the cGAS-STING signaling cascade in mouse microglial cells, suggesting this mechanism may underlie multiple tauopathies such as Alzheimer's disease." (PMID 41049538, 2025). "While the cGAS/STING pathway is critical for innate immunity, abnormal activation of this pathway has been increasingly implicated in various human diseases including Parkinson’s and Alzheimer’s diseases, as well as normal aging." (PMID 38177926, 2024). "In the CNS, excessive or chronic cGAS/STING activation in microglia leads to inflammation and neurodegeneration and is implicated in multiple neurodegenerative diseases, such as ataxia telangiectasia, Parkinson’s disease, amyotrophic lateral sclerosis, and Alzheimer’s disease." (PMID 37206668, 2023). "This work reveals the relationship between the cGAS‐STING signaling pathway and the pathological mechanisms of Alzheimer's disease.The role of the cGAS‐STING signaling pathway in AD pathology." (PMID 41376208, 2025). "In addition, TSG can reduce the formation of NLRP3 inflammatory vesicles by inhibiting the activation of the cGAS-STING pathway, thereby reducing the neuroinflammatory response and demonstrating its potential therapeutic value in Alzheimer’s disease." (PMID 39737190, 2024). "Further mtDNA, an important source for activation of the cGAS-STING signaling pathway, has been shown to participate in many ROS related metabolic disorder diseases, such as lumbar disc degeneration, kidney fibrosis, and Alzheimer’s disease (AD)." (PMID 38735970, 2024). "Notably, the cGAS-STING pathway, a central regulatory hub of innate immunity, has been demonstrated to drive inflammatory cascades in neurodegenerative diseases such as Alzheimer’s disease and Parkinson’s disease." (PMID 40903460, 2025).
diabetes (26 papers, 2021 to 2026). "This study aims to investigate the role of mitochondrial DNA (mtDNA)-mediated cGAS-STING activation in promoting diabetes-associated atrial fibrillation (AF) through cardiomyocyte-macrophage crosstalk." (PMID 41356195, 2026). "Despite these advances, the precise mechanisms governing cardiomyocyte-macrophage interactions and the pathogenetic contributions of cGAS-STING signaling in diabetes-associated AF remain incompletely characterized." (PMID 41356195, 2026). "Although research has yet to clearly define the role of cGAS/STING degraders in diabetes and its associated cardiovascular complications, their established function within the cGAS-STING signaling pathway suggests significant potential." (PMID 41020872, 2025). "The cGAS-STING signaling pathway plays a critical role in mediating cardiovascular complications associated with diabetes, particularly in DCM, MI/RI, and vascular endothelial injury." (PMID 41020872, 2025). "The cGAS–STING signaling pathway was also reported to be associated with diabetes through Akt and DsbA‐L, but the study was only a correlation analysis, and no definitive evidence has been found." (PMID 38525112, 2024). "We confirmed that sterile inflammation is the underlying cause of diabetes and obesity in db/db mice and showed that the activation of the cGas-STING pathway and the resulting upregulation of Irf7 takes place as early as at 8 weeks of age." (PMID 37979047, 2024). "Because there are few studies on the cGAS-STING pathway and diabetes, with some indirect literature reports, we can still observe that the cGAS-STING pathway is inextricably linked with diabetes and its complications." (PMID 38312740, 2024). "The hyperglycemic microenvironment of diabetes causes cells to suffer from oxidative stress, and cGAS-STING is also involved, especially when the leakage of mtDNA from aging cells is more pronounced." (PMID 38312740, 2024). "These in vitro findings strongly suggest that effective treatment of diabetes-associated atrial inflammation may require dual targeting of both mitochondrial oxidative stress and the cGAS-STING signaling pathway." (PMID 41356195, 2026). "Studies indicated that TCM has a potential effect on mitigating glucose and lipid metabolic irregularities in diabetes by regulating the cGAS‐STING pathway." (PMID 41250907, 2025). "Evidence shows that cGAS-STING is over-activated in diabetes and its complications, when the leakage of mtDNA in elderly mice is more serious." (PMID 38312740, 2024). "Altered expression of mitochondrial transcription factor A, TREX1, and activity of the cGAS/STING pathway in diabetic kidneys." (PMID 39589791, 2024). "It is established that during the development of diabetes, the morphological and functional properties alter, leading to the increased mtDNA leak into the cytosol and activation of the cGAS-STING signaling, exacerbating the MI impacts." (PMID 39664570, 2024). "Our previous study revealed that lipotoxicity-induced mtDNA release activated the cGAS-STING pathway in cardiomyocytes in obesity-related diabetes." (PMID 38129863, 2023). "To further elucidate the molecular mechanism(s) by which STING promotes diabetes-induced retinal vascular cell injury, we investigated the role of downstream effectors of the cGAS/STING pathway, including TBK1 and IRF3." (PMID 37345657, 2023). "Dysregulation of the cGAS/STING pathway has been implicated in a variety of diseases, including diabetes, lupus, arthritis, and some types of cancer." (PMID 37345657, 2023). "Since this report only addressed STING, further studies are warranted to determine the usefulness of the cGAS–STING pathway in diabetes." (PMID 34906241, 2021). "While the cGAS-STING pathway's role in diabetic AF remains unclear, studies show that STING knockout or inhibition reduces diabetes-related cardiac inflammation by suppressing NLRP3 inflammasome activation." (PMID 41356195, 2026).
diabetes (continued). "Through integrated transcriptomic, in vivo, and in vitro approaches, we demonstrate that diabetes disrupts MQC, causing excessive leakage of mtDNA and subsequent elevation in phosphorylation levels of key molecules in the cGAS-STING signaling pathway in both atrial myocytes and macrophages." (PMID 41356195, 2026). "Collectively, these findings underscore the cGAS-STING signaling pathway as a critical regulator of immune-inflammatory responses in DCM, emphasizing its potential as a therapeutic target for alleviating complications associated with diabetes." (PMID 41020872, 2025). "Based on the current body of research, traditional Chinese medicines and their active monomer components show immense potential in the prevention and treatment of myocardial injury in diabetes-related cardiovascular complications mediated by the cGAS-STING signaling pathway." (PMID 41020872, 2025). "Thus, the cGAS-STING pathway is intricately involved in multiple modes of cell death in diabetes, contributing to a complex interplay of inflammation, cell death, and metabolic dysregulation." (PMID 41020872, 2025). "Moreover, there is evidence indicating that the cGAS‐STING pathway is overactivated in diabetes and its complications." (PMID 39365284, 2024). "Whether the same situation exists in other complications of diabetes mellitus, which links cGAS-STING with pyroptosis, needs further research to verify." (PMID 38312740, 2024). "We speculate that the depletion of renal mtTFA and TREX1 in diabetes paved the way for DNA to stimulate the cGAS/STING pathway." (PMID 39589791, 2024). "And modulation of reprogramming through the cGAS-STING pathway to alleviate chronic inflammation in diabetes may be a potential treatment option for diabetic complications." (PMID 38312740, 2024). "A couple of earlier studies also showed that diabetes increased mitDNA damage and the glycation level of mtDNA repair enzyme, which also indirectly indicates the potential activation of the cGAS–STING pathway owing to the presence of damaged mitDNA and mitochondria in the heart of diabetic mice." (PMID 34906241, 2021). "Lastly, is it possible to treat diabetes by targeting the cGAS–STING pathway?" (PMID 34906241, 2021). "Therefore, in this section, we will briefly discuss diabetes-induced complications and highlight the potential link between the cGAS–STING pathway and these diabetic complications." (PMID 34906241, 2021). "Here we provide evidence that increased expression of STING in the retina of human DR donors is associated with an increased level of free DNA in patients with DR, suggesting that the activation of cGAS/STING signaling in diabetes may be due to the accumulation of free DNA in the eye." (PMID 37345657, 2023). "Moreover, since this study only focused on T1DM in NOD mice, it is urgent to address whether the cGAS–STING pathway can work in other types of diabetes." (PMID 34906241, 2021). "In conclusion, the cGAS–STING axis serves both as a pathological driver and a potential protective modulator in diabetes-related cardiovascular diseases." (PMID 41020872, 2025). "Several small-molecule inhibitors targeting cGAS or STING have recently been developed and show promise for dampening inflammation in diabetes and DWH." (PMID 38312740, 2024). "Further studies focused on cGAS-STING mechanisms and therapeutic inhibition can unveil new directions to address this serious complication of diabetes." (PMID 38312740, 2024). "Taken together, this study revealed that decreased mitochondrial fusion-mediated mitoDNA cytoplasmic enrichment, activation of the cGAS-STING pathway, and phosphorylation of the TBK1-IRF3 pathway are important contributors to MI/R injury in diabetes." (PMID 37537600, 2023). "Here, we will selectively summarize some literature reports on the effects of the cGAS–STING pathway in different organ diseases and focus on the possible cross-talk between the cGAS–STING pathway and diabetes." (PMID 34906241, 2021).